STAT3 (signal transducer and activator of transcription 3)
Diseases named in the same sentence as STAT3 in open-access papers (continued):
Sharing a sentence is not in itself a finding about the gene and the disease.
tumor (continued). "This becomes increasingly complex when considering the role of STAT3 in non-tumor cells in metastasis (i.e., the tumor microenvironment), as cancer drugs rarely discriminate normal cells from tumor cells." (PMID 24995503, 2014). "In the colon, activation of the Wnt signalling pathway is usually an ‘early’ event involved in tumour initiation, whilst activation of STAT3 signalling is considered a ‘late’ event involved in tumour invasion and metastasis." (PMID 25348333, 2014). "Curcumin is known to have anti-tumor effects via the STAT3 signaling pathway; however its use is limited by its poor bioavailability." (PMID 25594014, 2014). "Upon STAT3 deletion tumor growth is significantly enhanced when compared to STAT3-expressing controls." (PMID 24473086, 2014). "We then exposed tumor cells to IL-6 in the presence of chemical inhibitors of STAT3, Akt, or ERK pathways and analyzed the phosphorylation responses." (PMID 24533454, 2014). "Src is commonly hyper-activated in human cancers and promotes metastasis in part by inducing tumour angiogenesis via a signal transducer and activator of transcription 3 (Stat3)/vascular endothelial growth factor (VEGF)-A signaling pathway." (PMID 25231728, 2014). "As will become clear, STAT3 can directly regulate genes leading to multiple tumor promoting processes from cell survival, invasion, angiogenesis, and immune escape." (PMID 24743777, 2014). "STAT3 regulates the expression of TGF-β and IL-10, crucial cytokines that contribute to the presence of tumor-associated Treg." (PMID 23720663, 2013). "When STAT3-depleted DCs were injected into immunosuppressive tumor microenvironment, stronger anti-tumor effects than wild type DCs were observed along with induction of stronger IFN-γ producing Th1 and CTL." (PMID 23755373, 2013). "While myeloid cells and activated T cells release pro-angiogenic factors such as VEGF, results from our study clearly show that B cells are an important producer of STAT3-donwstream pro-angiogenic factor in the tumor microenvironment." (PMID 23734190, 2013). "In summary, gastric stromal fibroblasts produced IL-6 in response to stimulation from tumor cells through IL-1 signaling in gastric tumorigenesis, and that secreted IL-6 promotes tumor growth through STAT3 activation." (PMID 23593346, 2013). "By pre-treatment of the NPC cells with berberine, activation of STAT3 induced by tumor-derived fibroblasts was suppressed." (PMID 24380387, 2013). "Nonetheless, we show that tumor-infiltrating B cells are critical for STAT3 activation and for angiogenic processes in the tumor microenvironment." (PMID 23734190, 2013). "Evidences also supported that STAT3 signaling triggered the crosstalk between tumor cells, TAMs were crucial for the regulation of malignant progression." (PMID 23825527, 2013). "We have initiated these studies for the purpose of studying the immunoregulatory activities of MSC and tumor cells, and demonstrated a contact-dependent mechanism for STAT3 activation that induces regulatory APC." (PMID 24073274, 2013). "Treatment with gemcitabine resulted in significantly smaller tumors in mice implanted with shSTAT3 cells indicating that a combination of gemcitabine and knockdown of STAT3 results in a significant reduction of tumor growth over either one alone." (PMID 24025152, 2013). "STAT3, activated by pro-inflammatory cytokines like IL-6 from tumor-infiltrating myeloid cells, promotes both survival and growth of transformed intestinal epithelial cells." (PMID 23940556, 2013). "Together, these findings define a novel role of B cells in promoting tumor progression through angiogenesis and identify STAT3 in B cells as potential therapeutic target for anti-angiogenesis therapy." (PMID 23734190, 2013). "Immunosuppressive molecules released by tumor cells can activate STAT3 in immune cells, leading to tumour-induced immunosuppression." (PMID 23819113, 2013).
tumor (continued). "Transfecting IL-17 into hepatocellular carcinoma cells significantly promotes neoangiogenesis, neutrophils recruitment, and tumor growth via AKT-dependent IL-6/JAK2/STAT3 signaling pathway in vivo." (PMID 24382972, 2013). "Hsp72 from tumor-derived exosomes was shown to promote STAT3-dependent immunosuppressive function of MDSCs in a TLR2/MyD88 dependent manner." (PMID 24066282, 2013). "While STAT1 increases the rates of apoptosis, improves functioning of the immune system and functions as a tumor suppressor by reducing cancer proliferation, STAT3 maintains the malignant transformation by increasing the proliferation of tumors." (PMID 23708675, 2013). "Selective Jak1 and Jak2 inhibitors can also inhibit Il-6/Stat3 signaling and concomitantly reduce tumor growth in xenograft models." (PMID 23520493, 2013). "Additional STAT3 targets include genes that promote cell proliferation, like Cyclins B and D, and c-Myc, which explains the reduced tumor sizes upon STAT3 ablation." (PMID 23940556, 2013). "In contrast, targeting STAT3 blocks tumor growth, invasion and metastasis formation in variety of cell lines both in vitro and in vivo." (PMID 24199193, 2013). "Mechanistically, we showed that AZD1480 inhibits the JAK/STAT3 pathway as measured by suppression of several specific, well-established downstream transcriptional targets of STAT3 in cells in vitro and in tumor xenografts in vivo." (PMID 23531921, 2013). "miR-125b-5p targets multiple genes involved in the regulation of apoptosis including BAK1, BCL3, PUMA and STAT3, but depending on the cell type, miR-125b-5p contributes either to oncogenesis or to tumor suppression." (PMID 23527180, 2013). "MAPK and STAT3 pathways are highly involved in tumor cell migration and invasion where their activation induces MMPs expression leading to the degradation of extracellular matrix proteins." (PMID 23593315, 2013). "Tumor cell-derived soluble factors and direct cell-cell contact with tumors cells induce strong STAT3 activation in macrophages." (PMID 24314323, 2013). "Since gefitinib has been shown to induce STAT3 activation and subsequent Akt recovery, we went to assess the anti-tumor efficacy of combinational inhibition of EGFR and STAT3." (PMID 24280348, 2013). "AZD1480 blocked endogenous constitutive and cytokine-induced activation of STAT3 in vitro and inhibited the activation of STAT3 in tumor xenografts." (PMID 23531921, 2013). "We demonstrate that the repression of CD44 by BXL0124 contributes to the inhibition of STAT3 signaling and tumor invasion in MCF10DCIS cells." (PMID 23326564, 2013). "Stat3 is an important oncogene in various human cancers and the TF-activated coagulation is required for primary tumor growth." (PMID 24086497, 2013). "When Stat3 was functionally ablated in B cells in the tumors, the overall Stat3 activity and expression levels of several angiogenic genes in the whole tumor were decreased." (PMID 23734190, 2013). "We demonstrated that the STAT3 transcription factor-regulated signaling pathway, which can be elicited upon exposure of tumor cells to chemotherapeutics, was partly activated by daunorubicin in AML cells." (PMID 24283803, 2013). "In the current study, we define a crucial role of B cells as well as their STAT3 activity as important contributors for tumor progression and tumor angiogenesis." (PMID 23734190, 2013). "Given the role of STAT3 in modulating tumor viability, radiosensitivity, and chemosensitivity, the development of an efficient STAT3 inhibitor is critical in the development of novel treatment regimens for solid tumors." (PMID 23382914, 2013). "The activation of STAT3 signaling was reported to play important roles in the induction of aggressive tumor behavior and EMT changes in cancer, including cancers in the upper aerodigestive tract." (PMID 23561329, 2013).
tumor (continued). "Consistent with our findings, previous paper indicated that IL-17 induces IL-6 production by tumor cells and stromal cells, which in turn activated Stat3." (PMID 24453427, 2013). "We also demonstrated using the Stamper-Woodruff assay that Stat3-induced TF expression promotes tumor cell adhesion to lung tissues." (PMID 24086497, 2013). "More and more evidences demonstrate the significance of Signal transducers and activators of transcription 3(STAT3) in oncogenesis and tumor development." (PMID 23590999, 2013). "This priming process induces secretory patterns that consistently feed back to activate oncogenic EGFR- and STAT3 pathways in tumor cells." (PMID 23597096, 2013). "This highlights the importance of determining the role of STAT3 activation in tumor stem cell behavior as well as the effects of initiating this pathway on tumor growth." (PMID 24376586, 2013). "Stat3-transformed cells gain the ability to form colonies in soft agar, and inhibition of TF signaling suppresses tumor growth." (PMID 24086497, 2013). "Mostly from mouse studies, the JAK2/STAT3 signaling pathway has emerged as a “master switch” of tumor-induced immune suppression." (PMID 24324467, 2013). "Our recent studies have also demonstrated that STAT3 mediates multidirectional crosstalk among tumor cells, endothelial cells and myeloid cells in promoting tumor angiogenesis." (PMID 23734190, 2013). "Membrane receptors known to interact with CD44 and their downstream signals activate Stat3 leading to tumor progression and invasion." (PMID 23401782, 2013). "The tumor suppressive role of PKCζ in K-ras-mediated lung tumorigenesis is mediated by repression of STAT3 activation in the tumor cells." (PMID 24015205, 2013). "STAT3 activation has a major role in protecting the tumor cells from body's immune surveillance during their transit through circulation." (PMID 24199193, 2013). "The ability of STAT3 inhibitors to induce apoptosis in both cancer stem cell and bulk tumor populations makes them potentially attractive therapeutic agents." (PMID 24376586, 2013). "During tumor development and subsequent metastatic progression, the ability of tumors to invade the lymphovascular system is mediated by STAT3." (PMID 24103426, 2013). "Knocking-down STAT3 significantly reduced the tumor burden as evidenced by a slower tumor progression and further reduced the growth of tumors that is associated with a reduction of Ki-67 positive cells." (PMID 24025152, 2013). "By promoting tumor cell survival and growth, STAT3 serves as a signal integrator to enable transformed cells to survive and proliferate in response to stimuli originated from stromal cells in tumor microenvironment." (PMID 23940556, 2013). "Researchers also found that interrupting STAT3 signaling in TME induced tumor cells to produce soluble factors capable of mediating bystander tumor cell killing." (PMID 23825527, 2013). "Acetylated STAT3, which recently attracted attention as a tumour-promoting factor, was also constitutively expressed by the four cell lines and had its expression markedly reduced by resveratrol." (PMID 23372833, 2013). "STAT3 regulates survival of tumor cells by activating genes that confer resistance against apoptosis." (PMID 23940556, 2013). "We found that the size of B16-F10 inoculated tumor in wild-type mice was significantly reduced with treatment of Stat3 inhibitor WP1066." (PMID 24453427, 2013). "It was reported that butein exhibited antiproliferative effects against tumor cells through suppression of the signal transducer and activator of transcription 3 (STAT3) activation pathway." (PMID 23690855, 2013). "Of the 309 unique, validated mutations identified through sequencing of the TCGA GBM tumor samples, CTNNB1, EP300, STAT3, and TOP1 also appear in the 50-gene subnetwork signature." (PMID 24068912, 2013).
tumor (continued). "This is consistent with our finding that acetylated STAT3 decreased in NK cell lines treated with resveratrol and supports the concept that STAT3 deacetylation is a contributing anti-tumour property." (PMID 23372833, 2013). "HCMV US2.8 is a chemokine receptor homologue that induces COX-2 expression, VEGF production, STAT3 phosphorylation and IL-6 production, all of which are relevant in tumor biology." (PMID 23451089, 2013). "Our work describes pro-tumorigenic marker proteins that identify tumor-supportive mononuclear cells and establishes a basis for therapeutic intervention aimed at neutralising these STAT3 and EGFR activators at the molecular level." (PMID 23597096, 2013). "Immunofluorescent staining of sections prepared from Matrigel plugs also showed the promoting effect of Stat3+/+ B cells on tumor angiogenesis." (PMID 23734190, 2013). "STAT3 also contributes to T cell-mediated tumor angiogenesis, since inhibiting STAT3 in T cells halts tumor growth in part by inducing collapse of blood vessels." (PMID 23734190, 2013). "To confirm that these data are not phenomena of cultured cell lines, we assessed TNF-α-induced STAT3 activation in human GBM cells maintained in an environment similar to the tumor microenvironment." (PMID 24244348, 2013). "In fact, STAT3 inhibition has been suggested as a good strategy to promote the control of cell proliferation and, consequently, tumor growth and metastasis formation." (PMID 23738079, 2013). "Protein analysis of tumor tissue lysates from three mice in each treatment group indicated that niclosamide blocks erlotinib-stimulated STAT3 phosphorylation leading to decreased Bcl2 and Bcl-XL levels." (PMID 24019973, 2013). "S1PR1 has been shown to mediate persistent activation of signal transducer and activator of transcription-3 (STAT3) in tumor." (PMID 24286034, 2013). "In our experiment, Stat3 activity in B16 tumor from wild-type and IL-17−/− mice was examined by immunofluorescence staining of phosphorylated Stat3 (p-Stat3)." (PMID 24453427, 2013). "Among these proteins, STAT3 is often constitutively activated and contributes to tumor progression and resistance to apoptosis in both solid and hematological malignancies." (PMID 24025152, 2013). "Nonetheless, scoparone efficiently suppressed the growth of DU145 xenografts in nude mice, accompanied by reduced phosphorylation of STAT3, implying that its anti-tumor efficacy in vivo is mediated through inhibition of STAT3." (PMID 24260381, 2013). "Deletion of IL-6 or its cognate receptor gp130 in AOM/DSS model resulted in reduced tumor size and tumor number, whereas further potentiation of STAT3 activity by introducing hyper-active gp130 led to increased tumor diameter and tumor count." (PMID 23940556, 2013). "Interleukin-27 signaling is mediated by the JAK-STAT pathway via activation of STAT1 and STAT3, which have tumor suppressive and oncogenic activities, respectively." (PMID 24274066, 2013). "BCL-XL, an anti-apoptosis gene, was similarly elevated in the tumor tissues with co-transplanted with TILs, which were also downstream transcripts of STAT3 activation and potentially explains the tumor growth enhancement." (PMID 23379788, 2013). "Treatment of Stat3 inhibitor WP1066 in B16-F10 tumor cells inoculated wild-type mice resulted in reduced proliferating cells, decreased blood vessels, and low percentage of CD11b+Gr-1+ MDSCs." (PMID 24453427, 2013). "Using immuno-fluorescence intracellular staining, we have previously demonstrated that both tumor cells and hMSC induce STAT3 phosphorylation and activation in APC (both DC and monocytes) in a contact dependent manner." (PMID 24073274, 2013). "Recently, sorafenib has been shown to suppress tumor growth by decreasing STAT3 phosphorylation in a group of human malignancies, including HCC." (PMID 23895220, 2013). "The early inhibition of STAT3 activity correlated well with Icaritin-induced inhibition of tumor cell proliferation." (PMID 24324713, 2013).
tumor (continued). "Our main focus was on the paracrine release of both EGFR and STAT3 activators by monocytes/macrophages to tumor cells." (PMID 23597096, 2013). "Inhibition of tumorigenic growth of NPC cells in vivo was correlated with effective inhibition of STAT3 activation in NPC cells inside the tumor xenografts grown in nude mice." (PMID 24380387, 2013). "Icaritin treatment (10 mg/kg) of Renca tumor-bearing mice resulted in potent inhibition of tumor growth, which correlated with a reduction in STAT3 activity in tumors and a reduction in Bcl-xL and Cyclin E protein expression." (PMID 24324713, 2013). "STAT3 is also an important transcription regulator, defining a transcriptional program at multiple levels that facilitate tumor cell proliferation, survival, invasion, cancer-promoting inflammation, and suppression of antitumor immune responses." (PMID 23864876, 2013). "Blocking STAT3 activity using techniques such as: antisense, RNA interference, dominant negative STAT3 and small molecular inhibitors reduced cancer cell growth, invasion, and tumor size in vivo and increased apoptosis in vitro." (PMID 24170218, 2013). "Although addition of Stat3−/− B cells to B16 tumor cells increased blood vessel formation somewhat, it was highly significantly less compared to that by adding Stat3+/+ B cells to B16 tumor cells." (PMID 23734190, 2013). "The correlation of G6PD expression and tumor growth corresponded with STAT3/STAT5 expression, although further experiments will be required to confirm the direct regulatory role of G6PD on this pathway." (PMID 23693134, 2013). "STAT3 is constitutively activated in many tumor types and this activation promotes acceleration of cell proliferation, upregulation of survival factors, and activation of anti-apoptotic proteins." (PMID 23663277, 2013). "Taken together, we have demonstrated the importance of B cells in promoting tumor progression, and B cells and/or their intrinsic STAT3 activity as targets for anti-angiogenic therapies." (PMID 23734190, 2013). "STAT-3 activation in immune cells also exerts an immunosuppressive effect, thus counteracting anti-tumor immune response." (PMID 23533994, 2013). "Taken together, these data indicate that Icaritin inhibited tumor STAT3 activity, resulting in significantly reduced tumor growth and inhibition of tumor vasculature in RCC tumors in vivo." (PMID 24324713, 2013). "Stat3 ablation in hematopoietic cells or treatment with CpG-Stat3 siRNA efficiently abolishes Stat3 activity in myeloid cells and B cells, leading to reduction of tumor burden and/or metastasis in mice." (PMID 23734190, 2013). "IL-6/STAT3 signaling has been identified to link with the transition of HR and aggressive tumor behavior." (PMID 23806095, 2013). "The same study also showed that inhibition of STAT3 acetylation by resveratrol results in promoter demethylation, restoring the expression of tumour suppressor genes." (PMID 23372833, 2013). "Further mechanistic studies revealed that resveratrol inhibited tumor growth and induced apoptosis by suppressing STAT3 signaling." (PMID 24199193, 2013). "Inhibition of STAT3, though disruption in activation or expression, leads to cessation of tumor cell growth and apoptosis." (PMID 24103426, 2013). "Constitutive STAT3 activation promotes tumor growth and survival, as well as invasion, epithelial-mesenchymal transition and angiogenesis." (PMID 23658720, 2013). "In summary, our study demonstrates that miR-124 serves as a tumor suppressor by inhibiting translation of STAT3 mRNA." (PMID 23940556, 2013). "Inhibition of STAT3 by miR-124 leads to increased cell apoptosis both in vitro and in vivo, and contributes to reduced tumor growth from transplanted human CRC cells." (PMID 23940556, 2013). "From a panel of tumor-associated suppressive factors (including PGE2), we found only IL-6 and IL-10 to induce STAT3 phosphorylation during human MoDC development." (PMID 24324467, 2013).